MTOR (mechanistic target of rapamycin kinase)
Diseases named in the same sentence as MTOR in open-access papers (continued):
Sharing a sentence is not in itself a finding about the gene and the disease.
tumor (continued). "This suggests that LMS with high levels of PI3K/mTOR pathway activation display low tumour T‐cell infiltration and increased infiltration of M2‐like polarised macrophages or mast cells." (PMID 38711203, 2024). "For instance, inhibitors of the PI3K-Akt-mTOR pathway can modulate T cell activation and differentiation, enhancing anti-tumor immunity." (PMID 39161771, 2024). "Tumor endothelial cells secrete IL-6 and CSF-1 which promote anti-tumor alternative macrophage polarization by triggering Akt1/mTOR pathway, resulting in anti-inflammatory and pro-tumorigenic macrophage activation." (PMID 38576482, 2024). "More importantly, a combination with small-molecule inhibitors of CDK4/6 (palbociclib, abemaciclib, or ribociclib), PI3K (alpelisib or inavolisib), or mTOR (everolimus) produced robust tumor regressions in most cases." (PMID 39767607, 2024). "In some cases, Rictor overexpression has been found at a higher rate than RICTOR amplification, which can be explained by other genetic alterations in the mTOR pathway, epigenetic changes, or miRNA expression aberrations in the tumor cells." (PMID 38339294, 2024). "Co-operation of an IAP antagonist with inhibitors of the PI3K/AKT/mTOR pathway to enhance anti-tumour activity has been previously reported." (PMID 39739112, 2024). "The genomic landscape of baseline tumor biopsies in this trial spanned the spectrum of genes and pathways (RTK, MAPK, PI3K/AKT/mTOR, cell cycle, and ER pathways) known to be associated with resistance to CDK4/6 inhibitors and endocrine therapy." (PMID 38503755, 2024). "Targeting autophagy mediated by the PI3K/AKT/mTOR pathway can enhance drug sensitivity and prevent drug resistance in tumor cells." (PMID 38318160, 2024). "This combination therapy demonstrated increased anti-tumor activity, suggesting a potential synergistic effect between mTOR and MEK inhibition in MM treatment." (PMID 38961036, 2024). "MASL treatment upregulated TNF-α, Fas, and FasL expression levels, while suppressing anti-apoptotic NF-κB and mTOR pathways in tumor cells." (PMID 39683650, 2024). "PI3K inhibitors function by inhibiting the activity of PI3K, thereby blocking downstream signalling cascades, such as AKT/mTOR, and impeding tumour growth and survival." (PMID 38722288, 2024). "The phosphatidylinositol-3-kinase (PI-3K)/Akt/mTOR pathway plays a pivotal role in regulating cell proliferation, growth, motility, angiogenesis, and survival in tumor cells." (PMID 39204369, 2024). "Our data suggest that GPX3 mediates the AMPK/mTOR signaling pathway by regulating the level of ROS in tumor cells and triggering an imbalance of oxidative stress in the organism." (PMID 38322113, 2024). "And upregulated SAT1 in TNBC was verified to facilitate tumor progression through the SAT1/YBX1/mTOR axis." (PMID 39073262, 2024). "In breast cancer, the lncRNA HOTAIR acts as a molecular scaffold to facilitate the assembly of the mTOR signaling complex, promoting tumor growth." (PMID 38279330, 2024). "When administered with LY294002, an inhibitor of the PI3K/AKT/mTOR pathway, the tumor’s ability to proliferate, migrate, and invade was greatly suppressed, and the EMT process was generally reversed." (PMID 38980538, 2024). "Recognizing the essential role of the PI3K/AKT/mTOR signaling pathway in tumor growth, which influences key cellular functions including survival, proliferation, metabolism, invasion, and angiogenesis, we explored how overexpressing HSPB6 affects this pathway." (PMID 39608715, 2024). "XHP downregulated tumor stem cell markers through modulation of the CD133/EGFR/Akt/mTOR pathway and inhibited tumor stem cell enrichment and self-renewal, preventing the malignant progression of glioma." (PMID 38957318, 2024). "High MAEL expression was associated with an anti-inflammatory tumor immune microenvironment and VEGFR/mTOR activation in ccRCC tissues and high sensitivities to VEGFR/PI3K-AKT-mTOR inhibitors in ccRCC cell lines." (PMID 38301040, 2024).
tumor (continued). "PI3K/Akt/mTOR signaling is one of the most critical regulators of various cellular process, particularly in controlling cell cycle and tumor progression." (PMID 39092293, 2024). "Most interestingly, AA appears to regulate Pdcd4 through the PI3K/Akt/mTOR/p70S6K signaling pathway, which is well-known as a major pathway regulating tumor cell proliferation, apoptosis, and migration." (PMID 38610995, 2024). "Autophagy helps tumor cells overcome nutrient deficit and enhances survival at the premature stage but suppresses tumor promotion through the activity of ROS and mTOR signaling pathways after tumor growth." (PMID 39595208, 2024). "When hyperactivated, mTOR signalling facilitates cell proliferation and metabolism, which contribute to both tumor initiation and progression." (PMID 39203892, 2024). "IHC assay demonstrated that the expression of p-Akt (Thr308) and p-mTOR (Ser2448) was significantly down-regulated in the transplanted tumor tissues highly expressing CARMN." (PMID 39558374, 2024). "Studies suggest that glucose deprivation induces abnormal fucosylation of membrane glycoproteins mediated by FUT1, thereby sustaining tumor cell stemness through the AKT/mTOR/4E-BP1 signaling pathway." (PMID 38230205, 2024). "TAC tends to further enhance this already elevated mTOR activity, which can contribute to tumour development in the remaining kidneys of KTRs during IS therapy after transplantation." (PMID 38341510, 2024). "mTOR, always overexpressed in the tumor, and controlling cell growth and metabolic activities, has an important role in both autophagy and ferroptosis." (PMID 38583115, 2024). "Molecular characterization of this tumor revealed high levels of phosphorylated mTOR (pMTOR); therefore, a therapy based on an mTOR inhibitor (everolimus) was administered." (PMID 39336782, 2024). "The MAPK and PI3K/Akt/mTOR signaling pathways are highlighted for their roles in tumor growth and resistance mechanisms." (PMID 39200315, 2024). "In fact, the PI3K/Akt/mTOR pathway plays an important role in tumorigenesis and the tumor progression of NENs." (PMID 39201255, 2024). "In terms of KEGG pathways, overexpressed BCAT1 was positively associated with several tumor-related and angiogenesis-related pathways, such as JAK/STAT signaling pathway, mTOR signaling pathway, VEGF signaling pathway, and TOLL like receptor pathway." (PMID 38309289, 2024). "In terms of tumor metabolism, mTOR’s role as a nutrient sensor is key due to its response to different nutrient cues such as glucose, amino acids, growth factors, and other stressors." (PMID 38892329, 2024). "This is interesting as in another study, tumor-derived exosomal miRNA let-7a is shown to affect insulin-Akt-mTOR pathway increasing OXPHOS metabolism and M2 polarization under hypoxia conditions." (PMID 39260692, 2024). "The primary function of Tsc1/2 as a tumor suppressor is to inhibit cell growth and proliferation by antagonizing the mammalian target of rapamycin (mTOR) pathway, a signaling network that is a regulatory hub for cell growth." (PMID 39352796, 2024). "Treatment of H3-K27M DMG xenograft mice models with this drug combination led to reduced tumor growth and confirmed downregulation of mTOR in vivo." (PMID 39093942, 2024). "Celecoxib, a nonsteroidal anti‐inflammatory drug, inhibited PNO1 expression and HCC tumour growth by regulating AKT/mTOR pathway." (PMID 38722284, 2024). "Studies have shown that another compound, quercetin, reduces tumor weight by targeting VEGFR2 through the Akt/mTOR/P70S6K signaling pathway." (PMID 38918540, 2024). "Recently, success has been reported with the mTor inhibitor everolimus in reducing tumor volume, but regrowth has been observed after dose reduction or cessation." (PMID 39030575, 2024). "The MAPK pathway also controls mTOR in the activation of pro-angiogenic/inflammatory chemicals in tumor cells." (PMID 39204369, 2024).
tumor (continued). "It has been proven that HIF-1 and protein kinase B (AKT) are capable of driving tumor growth despite mTOR and VEGF inhibition." (PMID 38339244, 2024). "Proximity to the blood vessels promotes the mammalian target of rapamycin mTOR-derived anabolic metabolism and enhances tumor aggressiveness and therapy resistance." (PMID 38473776, 2024). "The PI3K/AKT/mTOR/autophagy pathways play a crucial role in regulating tumor progression and maintaining the balance of the tumor microenvironment." (PMID 38590708, 2024). "The results of this study indicate that AS101 inhibits tumor migration by downregulating heparanase through the AKT/mTOR signaling pathway and has positive effects in vivo." (PMID 39247596, 2024). "Our findings revealed that knockdown of the MTOR gene not only inhibited the growth of ESCC tumor cells in vitro but also reduced the growth rate of subcutaneous tumors in a mouse model, thereby improving the survival rate of the mice." (PMID 39742278, 2024). "Extensive research has documented the role of the PI3K/mTOR pathway in promoting tumour cell intrinsic mechanisms of survival and proliferation." (PMID 38711203, 2024). "Gil claims that the overactivation of the PI3K/Akt/mTOR pathway can promote tumor growth and result in resistance to treatment." (PMID 39057437, 2024). "They found upregulation of mTOR pathway signals in FDG-avid tumours and that treatment with an mTOR inhibitor resulted in decreased FDG uptake followed by effective tumour control in both hyperglycolytic HCC cell lines and xenograft mouse models." (PMID 38760445, 2024). "Secondly, we evaluated the effects of Pazopanib alone, LY-294002 (AKT inhibitor) alone, Rapamycin (mTOR inhibitor) alone or in combination with si-circPDHK1 on the tumor biological behavior of ccRCC cells through CCK8, EdU, and transwell assays." (PMID 38360682, 2024). "Preoperative administration of mTOR inhibitors to large SEGAs and tumors occurring in deep, hard-to-reach brain structures helps reduce tumor size and enable complete resection." (PMID 39410026, 2024). "Progression of prostate cancer and multi-drug-resistant tumour was significantly associated with PI3kinase pathway hyperactivation, either due to PTEN modulation or due to hyperactivation of PIK3CA, AKT, mTOR or any other proteins of the pathway." (PMID 38774756, 2024). "Amplified signalling in the PI3K/AKT/mTOR pathway can promote tumour cell survival, proliferation, and metabolic adaptations that undermine anti-tumour immune responses." (PMID 39749035, 2024). "Altered regulation of the PI3K–Akt–mTOR signaling pathway is one of the key pathways driving the malignant process, and they are involved in tumor development by controlling various cellular functions." (PMID 38245763, 2024). "Studies have shown that the activation of the PI3K/AKT/mTOR signalling pathway, which can accelerate the cell cycle, inhibit apoptosis, and promote tumour cell migration is closely related to the occurrence of tumours." (PMID 38169650, 2024). "Nonetheless, the elimination of CSCs using mTOR inhibition remains a potent approach in anti-tumor therapy, and advanced tumor-targeting techniques with specificity are required for enhanced efficiency." (PMID 39349424, 2024). "By inhibiting mTOR, Everolimus reduces the growth and survival signals of tumor cells, leading to reduced cell proliferation and angiogenesis." (PMID 39772235, 2024). "Activation of the AMPK pathway, which is also known as the energy switch, inhibits the activity of downstream mTOR and affects the synthesis of glucose and proteins, thereby effectively inhibiting the growth and proliferation of tumor cells." (PMID 38268030, 2024). "The study discussed the preclinical and clinical data available for PI3K/AKT/ mTOR inhibitors, highlighting their potential to inhibit tumor growth and promote cell death in cSCC." (PMID 38655092, 2024).
tumor (continued). "Cytokines such as IL-4 and IL-13 within the tumor microenvironment regulate the polarization of tumor-associated macrophages (TAMs) through downstream Stat6-dependent inhibition of Arg1, activation of PPARγ, and TSC1-mediated inhibition of mTOR." (PMID 39676873, 2024). "mTOR is a serine/threonine kinase that frequently acts as a downstream mediator of PI-3K/Akt signaling in tumor cells." (PMID 39204369, 2024). "STING regulates the activity of TBK1 by directly interacting with TBK1 in innate immunity, whereas the TBK1-mediated mTOR signaling pathway plays an important role in tumor progression." (PMID 39061024, 2024). "In the present study, GEFT was found to positively regulate mTOR expression in RMS cells and to promote tumor progression to some extent through its ability to induce mTOR expression." (PMID 38225540, 2024). "The PI3K/AKT/mTOR is one of the numerous signaling cascades that govern multiple cellular and molecular processes fundamental to tumor initiation, invasion, and metastasis." (PMID 39430254, 2024). "Further experiments demonstrated that FOXC1 acted as a tumor suppressor to regulating AMPK/mTOR pathway." (PMID 39093497, 2024). "Meanwhile, the Akt pathway, in conjunction with neuroligin-3 (NLGN3) and the phosphoinositide 3-kinase (PI3K)-mammalian target of the rapamycin (mTOR) pathway, exerts profound effects on cell survival and growth regulation within the tumor microenvironment." (PMID 38732975, 2024). "Our results indicate that the upregulated lncRNA LINC01605 promotes PDAC tumor cell proliferation and migration by regulating cholesterol metabolism via activation of the mTOR signaling pathway in a LIN28B-interacting manner." (PMID 39048994, 2024). "Future works that determine if LMP2A activates mTOR/ p70 S6K/4E-BP1 to enhance HIF-1α and ATP production in pre-malignant cells would be important to understand the contribution of this pathway to tumor development in EBV-associated tumors." (PMID 38612754, 2024). "This pathway can be overactivated in GB due to the downregulation of PTEN, which physiologically acts as a tumor suppressor by inhibiting the PI3K/AKT/mTOR pathway." (PMID 39796096, 2024). "As the deregulation of mTOR is seen in multiple tumor types, the mTOR pathway represents a promising therapeutic target." (PMID 38474373, 2024). "Mechanistically, microglia facilitate TME immunosuppression, tumor immune evasion, and tumor MES transition through the mTOR-dependent regulation of STAT3 and NF-κB." (PMID 38891074, 2024). "Everolimus, another mTOR inhibitor similar to temsirolimus, has been evaluated in combination with bortezomib for its inhibitory effects on MM tumor cells." (PMID 38961036, 2024). "Downstream of the PI3K-Akt signaling pathway, mTOR regulates tumor growth, metabolism, immunity, and other processes." (PMID 38438907, 2024). "This study investigates the role of basic helix‐loop‐helix transcription factor 40 (BHLHE40) in pancreatic cancer (PCa), revealing its upregulation in tumor due to increased chromatin accessibility and mTOR pathway activity." (PMID 38064101, 2024). "For tumor cells, NETs have been reported to promote the tumor angiogenesis via activating the AKT/mTOR signaling in endothelial cell in gastric cancer." (PMID 38577608, 2024). "Sorafenib is a multi-kinase inhibitor that interferes with tumor-specific signaling pathways such as RAF/MEK/ERK or PI3K/Akt/mTOR." (PMID 39239650, 2024). "The combined targeting of mTOR and ferroptosis provides a potential intervention means for tumor cells." (PMID 38583115, 2024). "It has been demonstrated that ATF6 sustains activation of the mammalian target of rapamycin (mTOR) pathway, a vital element in tumor metabolism." (PMID 39080273, 2024).
tumor (continued). "Similar to our in vitro data, GZ17-6.02 suppressed the Pi3k/Akt/mTOR pathway in the subcutaneous tumor model." (PMID 38263212, 2024). "Multiplex immunofluorescence staining for pS6S240/244 confirmed successful attenuation of PI3K/mTOR signalling in tumours treated with PI3K/mTOR or PI3K/mTOR + PD‐1 inhibitors." (PMID 38711203, 2024). "Over and above, inflammatory response mediated by mTOR signaling has been highlighted in tumor immune microenvironment by promoting immune cell recruitment." (PMID 39290706, 2024). "Ongoing therapies in combination with mTOR inhibitors and their highest clinical trial phase in various tumor types based on the GlobalData database." (PMID 38515456, 2024). "To further confirm the role of the PI3K/AKT/mTOR/HIF-1α signaling pathway in TGFBI-mediated tumor promotion, we used the AKT activator SC79 to treat 786-O cells transfected with TGFBI siRNA." (PMID 39068456, 2024). "It was reported that CPH interferes with mTOR and β-catenin signaling pathways to exert its anti-tumor effects." (PMID 39522095, 2024). "Based on the western blot analysis of tumours, the mTOR pathway was activated in the vehicle control group and downregulated in the Cy + Rap group when compared with the control and Cy groups." (PMID 38734930, 2024). "Blocking the activity of a downstream target of AKT1, mTOR, using rapamycin, inhibited the pro-tumor effects of the fibroblast-derived melanosomes on macrophages." (PMID 38719996, 2024). "For example, mutations in the SPOP gene lead to increased stability of tumor-associated proteins like PTEN and enzymes involved in the PI3K/mTOR signaling pathway, enhancing cell proliferation." (PMID 39296545, 2024). "The PI3K/AKT/mTOR signaling pathway plays a crucial role in promoting tumor cell proliferation, migration, epithelial–mesenchymal transition (EMT), inhibiting cell apoptosis, and increasing sensitivity to chemotherapy drugs." (PMID 39119480, 2024). "Our previous study demonstrated that tumor suppressive miR-99b-5p negatively regulates the expression of androgen receptor (AR) and mTOR, potentially serving as a therapeutic agent for aggressive PCa." (PMID 38792011, 2024). "These mutations drive tumor growth and survival by activating the PI3K/AKT/mTOR pathway, which is essential for cell proliferation and survival." (PMID 39696683, 2024). "To date, the splicing mechanism for mTORβ as well as the role of mTOR splicing in tumor development remain elusive." (PMID 38671459, 2024). "For instance, the dual PI3K/mTOR inhibitor dactolisib has shown good efficacy in non‐clinical models, but clinical testing in various tumor types, including mCRPC (NCT01717898), has been discontinued due to toxicity." (PMID 39092562, 2024). "Dysregulated activation of the PI3K/AKT/mTOR signaling pathway affects a wide range of processes, including cell proliferation, metabolism, tumor cell differentiation, autophagy, and epithelial–mesenchymal transition (EMT)." (PMID 39014263, 2024). "HMGB1 plays a key role in the development of various tumors by regulating the PI3K/AKT/NF-κB/VEGF/EMT and AMPK/mTOR signaling pathways, and it can act as both a tumor suppressor and an oncogenic factor." (PMID 37897664, 2024). "In these cases, we recommend the immunohistochemical analysis of at least 3-4 in situ tissue markers [e.g., p-mTOR, p-S6, Rictor, and p-Akt (Ser473)] to provide a good representation of mTORC1 and mTORC2 activity in tumor tissue." (PMID 38515456, 2024). "In general, the mTOR pathway interacts extensively with other signaling pathways and in this way is involved in the regulation of tumor metabolism." (PMID 38933335, 2024). "This upregulation activates the PI3K/AKT/mTOR pathway, consequently fostering perineural invasion and facilitating lymph node metastasis, particularly in advanced tumor stages." (PMID 38081962, 2024).